IFT88 (intraflagellar transport 88)
Diseases named in the same sentence as IFT88 in open-access papers (continued):
Sharing a sentence is not in itself a finding about the gene and the disease.
situs inversus (1 paper, 2012). A congenital condition in which there is complete right-to-left reversal of the position of the major thoracic and abdominal organs (that is, they are arranged in a mirror image of the normal positioning). "Evidence for this ‘threshold hypothesis’ is provided by the observation that initial left-right determination is completely normal in the cbs mutant, but that a cross of the cbs allele to the full, targeted deletion of the Ift88 gene results in a 50% incidence of situs inversus." (PMID 23351706, 2012).
tauopathy (1 paper, 2023). Neurodegenerative disorders involving deposition of abnormal tau protein isoforms (tau proteins) in neurons and glial cells in the brain. "Even though we revealed Ift88 regulates EV secretion in microglial cells, the microglia in pathological conditions such as amyloidopathy and tauopathy also promote EVs with altered proteomic content, which should be addressed in future studies." (PMID 37942288, 2023).
cancer (17 papers, 2012 to 2025). A tumor composed of atypical neoplastic, often pleomorphic cells that invade other tissues. "Many studies have examined IFT88 function and demonstrated PC loss in many types of cancer associated with higher cancer aggressiveness." (PMID 38260150, 2023). "Decrease in cancer cell viability ≈5% and total cell number ≈20% was also measured in PC-deficient IFT88−/− cells." (PMID 36498831, 2022). "TUNEL-positive cancer cells within the IFT88-deficient TPC1 population showed loss of primary cilia." (PMID 33602982, 2021). "Osteoblasts secrete TNF-α to inhibit cancer cell proliferation, a mechanism regulated by osteoblasts’ IFT88." (PMID 40076734, 2025). "Collectively, cancer cell survival following VBL treatment is regulated by PC formation via AATF-mediated expression of IFT88 and NPHP3." (PMID 39408701, 2024). "We have shown that this signaling is blocked by inhibition of osteocyte primary cilia/IFT88 expression via cancer cell secretion of TGF‐β." (PMID 37967351, 2024). "This study provides a comprehensive mechanistic investigation regarding INTU and IFT88 downregulation in cancer, and further highlights the involvement of Hh signaling in carcinogenesis." (PMID 36084949, 2022). "We also found GIST to highly express four genes (KIF3A, IFT52, IFT88, and IFT172), which are associated with PC function in several cancers." (PMID 27793025, 2016). "Additionally, data from the GEPIA2 database revealed a significant upregulation of IFT88 in cancer tissues." (PMID 40388100, 2025). "Then, we prepared PC-deficient IFT88−/− A375 cells and examined VBL-mediated cancer cell death." (PMID 39408701, 2024). "We, therefore, sought to determine whether the inhibition of osteocyte regulation of cancer cell behavior was due to the reduced expression of osteocyte cilia/IFT88 or via another TGF‐β‐mediated pathway." (PMID 37967351, 2024). "Thus, we demonstrate that cancer cells suppress the expression of osteocyte primary cilia/IFT88 via the release of TGF‐β." (PMID 37967351, 2024). "The phenotype and protein expression alteration due to STIL silencing could be reversed by IFT88 silencing in cancer cells." (PMID 35155425, 2022). "Finally, we demonstrate the requirement of IFT88 for efficient centrosome clustering in a variety of cancer cell lines naturally harboring supernumerary centrosomes and its importance for cancer cell proliferation." (PMID 32270908, 2020). "Another inference from these results is that IFT88 may be a potential biomarker for tumor diagnosis or prognosis, which is consistent with the dysfunction of primary cilia in many human cancers." (PMID 31662980, 2019). "Cancer cells, in turn, secrete TGF-β to suppress the expression of the IFT88 gene in osteoblasts, thereby disrupting this inhibitory mechanism." (PMID 40076734, 2025). "We have shown that the disruption of cancer cell proliferation and migration by osteocytes is suppressed by release of TGF‐β from cancer cells, and that TGF‐β also disrupts osteocyte cilia and IFT88 expression." (PMID 37967351, 2024). "This anti‐proliferative mechanism is primary cilium‐ or IFT88‐dependent, and can be suppressed by TGF‐β released by cancer cells." (PMID 37967351, 2024). "Intraflagellar transport protein 88 homolog (IFT88), also known as TG737, is a protein known to suppress the invasion and migration of cancer cells when overexpressed." (PMID 35454982, 2022). "These modules contained several cancer regulators such as Intraflagellar Transport (IFT) complex proteins (IFT74, IFT88), BBSome complex proteins (BBS2, BBS7, BBS9, BBS12), exocyst complex components (EXOC3, EXOC4, EXOC6B, EXOC7, and EXOC8), TTC8, TTC21B, EVC, and NEK1." (PMID 40700427, 2025).
cancer (continued). "Additionally, the functions of IFT88 in cancer may also be associated with its non-ciliary-related roles, including the regulation of cell division (through spindle orientation and modulation of the cell cycle), the control of cell migration, and the establishment of immune synapses in lymphocytes." (PMID 40076734, 2025). "In addition, since IFT88 is a critical ciliary maintenance protein in ciliogenesis, we examined the role of ciliogenesis on VBL-mediated cancer cell death using PC-negative IFT88−/− cells." (PMID 39408701, 2024). "Furthermore, it shows that cancer cells block this mechanism by secreting transforming growth factor beta (TGF‐β), which disrupts osteocyte cilia and IFT88 gene expression." (PMID 37967351, 2024). "Finally, we demonstrate the importance of IFT88 and IFT52 for efficient centrosome clustering in cancer cell lines naturally harboring supernumerary centrosomes and the importance of IFT88 for cancer cell proliferation." (PMID 32270908, 2020). "Further, WB analysis of lysates from wt and cancer OSE cell cultures grown with or without serum demonstrated that IFT88 and IFT20 are expressed at similar levels in all three OSE cell lines." (PMID 23351307, 2012).
tumor (16 papers, 2012 to 2025). "To establish tumor spheroids, we infected cells with lentiviruses containing shRNA against IFT88 (five sequences, #1 to #5)." (PMID 39820281, 2025). "As unique signaling organelles, primary cilia can mediate or inhibit Hh pathway-dependent tumor development through IFT88, depending on the nature of the carcinogenic initiation events." (PMID 40076734, 2025). "IFT88 has also been shown to inhibit Che1, an inhibitor of the Rb tumor suppressor – upon IFT88 ablation, Che1 then inhibits Rb, freeing E2F transcription factors to drive cell cycle progression." (PMID 40301543, 2025). "In early metastasis, osteocytes secrete TNFα, mediated by IFT88 of their primary cilia, which suppresses tumor cell proliferation." (PMID 40301543, 2025). "The results confirmed that knockdown of KIF3A and IFT88 significantly inhibited ciliogenesis in tumor tissues." (PMID 39389955, 2024). "We next sought to explore the driving forces causing this downregulation in LUAD and UCEC tumor samples, and identified multifaceted mechanisms in the DNA, RNA and protein levels contributing to INTU and IFT88 downregulation." (PMID 36084949, 2022). "We therefore sought to delineate the underlying mechanisms of INTU and IFT88 downregulation in LUAD and UCEC tumor samples." (PMID 36084949, 2022). "Hierarchical cluster analysis of gene modules described by the GO terms ‘cell death’, ‘tumorigenesis of tissues’, and ‘cell proliferation of tumor cells’ clearly separated IFT88-knockdown samples from controls." (PMID 30345732, 2019). "Besides, the depletion of KIF3A and IFT88, genes required for ciliogenesis, significantly inhibited tumor proliferation and metastasis in vitro and in vivo." (PMID 39389955, 2024). "Our findings suggest that cooperation of NPHP3 and IFT88 may be required for PC formation via AATF binding to their promoters in tumor cells and underscore the need for further investigation of the involvement of AATF in the metastasis of ciliated tumor cells." (PMID 39408701, 2024). "Moreover, the expression of MALAT1 was found to be positively associated with the mRNA levels of INTU and IFT88 in LUAD and UCEC tumor samples." (PMID 36084949, 2022). "To unveil whether IFT88 silencing promotes tumor phenotype by activating autophagy, we used si-IFT88 and si-ATG7 to cotransfect HCC cells and then detected tumor properties." (PMID 31662980, 2019). "However, suppressing cilia formation in other GBM cell lines, by disrupting critical ciliogenesis genes such as KIF3A or IFT88, had variable effects on tumor growth in vitro and in vivo." (PMID 30410731, 2018). "Moreover, IFT88 silencing can markedly induce tumor cell proliferation, migration, and invasion." (PMID 31662980, 2019). "Furthermore, in a mouse subcutaneous tumor model, si-IFT88 treatment could obviously promote tumor growth along with the low expression of IFT88, higher level of proliferation marker Ki-67, and increasing autophagic flux." (PMID 31662980, 2019). "RNA was extracted from xenograft tumor tissues, followed by RT-qPCR analysis, which revealed reduced expression of both LRRC56 and IFT88 in the sh-LRRC56 tumors." (PMID 40388100, 2025). "Altogether, TCF4 was identified as a putative upstream regulator in controlling the expression of INTU and IFT88 in LUAD and UCEC tumor samples." (PMID 36084949, 2022). "We next evaluated the correlation between the miRNA level and INTU or IFT88 expression in LUAD and UCEC tumor samples." (PMID 36084949, 2022). "A group of Hh pathway-related genes, including INTU and intraflagellar transport 88 (IFT88), were enriched in LUAD and UCEC tumor samples." (PMID 36084949, 2022). "Taken together, this study demonstrates the prognostic significance of the Hh-related genes INTU and IFT88 in LUAD and UCEC and further delineates multifaceted mechanisms leading to INTU and IFT88 downregulation in tumor samples." (PMID 36084949, 2022).
tumor (continued). "Notwithstanding the potential extraciliary functions for KIF3A and IFT88, our findings suggest that GBM cilia play an important role in tumor growth and therapeutic resistance." (PMID 30410731, 2018). "In addition, INTU expression significantly correlated with the expression of IFT88 from LUAD and UCEC tumor samples." (PMID 36084949, 2022). "Moreover, we demonstrated novel TCF4 and ncRNA-involved mechanisms that contribute to the downregulation of INTU and IFT88 in LUAD and UCEC tumor samples." (PMID 36084949, 2022). "IFT88 depletion did not affect the size of the tumor spheroids." (PMID 39820281, 2025).
infection (4 papers, 2013 to 2025). The state of being infected such as from the introduction of a foreign agent such as serum, vaccine, antigenic substance or organism. "At 15 days after infection, we recovered roughly the same number of bacteria that was in the original inoculum in 70% of both control and IFT88 KO mice." (PMID 36505420, 2022). "In a series of experiments, IFT88 control mice and IFT88 KO mice received different preparations of Mabs lung inocula with lung CFU assessed out to approximately 8 weeks post-infection." (PMID 36505420, 2022). "The other notable findings in our agarose bead inoculum experiment were the significantly elevated levels of IL-1α and TNFα in IFT88 KO mice relative to control mice at day 15, with the difference still present and significant at day 54 after infection." (PMID 36505420, 2022). "Importantly, we demonstrate Mabs persistence in the lungs of mice with IFT88 deletion for at least 8 weeks after infection following a low dose infecting inoculum (approximately 3-4 months after deletion of IFT88)." (PMID 36505420, 2022). "Thus, in our next experiment using this Mabs agarose bead inoculum, we compared growth of Mabs in the lungs of control mice to growth in the lungs of IFT88 KO mice carried out to 54 days (approximately 8 weeks) post-infection." (PMID 36505420, 2022). "Of the proinflammatory cytokines assayed, IL-22 was noteworthy in that it was significantly elevated in IFT88 KO mice relative to IFT88 control mice in both the uninfected and Mabs-infected groups, suggesting an important role for this cytokine in our infection model." (PMID 36505420, 2022). "At day 20 after infection, we only recovered between 50 and 250 total lung CFU from both the IFT88 KO and control mice, and total lung CFU in all mice were below the limit of detection by day 36 after infection." (PMID 36505420, 2022). "The combined results from pooled infection assays, and separate infections with three individual mutants, showed that the IFT88 deletion mutants, which lacked external flagella, were completely avirulent." (PMID 40602995, 2025). "IL-17 was not significantly elevated in IFT88 KO mice compared to IFT88 control mice in either uninfected or infected mice in the absence of persistent infection." (PMID 36505420, 2022). "Furthermore, the decreased percentage of CD4+FoxP3+ T cells in the total lung lymphocyte population of IFT88 KO mice is not dependent on infection with Mabs and is apparent 3 months after deletion of the IFT88 gene (treatment with tamoxifen)." (PMID 36505420, 2022).
kidney disease (4 papers, 2017 to 2025). "Intraflagellar Transport 88, encoded by IFT88, is involved in cilium biogenesis and the genetic mutations carried on this gene were firstly associated with kidney disease." (PMID 34715892, 2021). "In mice, IFT88 is homologous to the kidney disease gene, Tg737." (PMID 34680887, 2021).
metabolic disorders (1 paper, 2021). "An early observation showing a correlation between metabolic disorders and neuronal primary cilia function was based on conditional tamoxifen-inducible KO of the core ciliogenesis gene Kif3a and the intraflagellar transport 88 (Ift88, also called Tg737) protein." (PMID 34211092, 2021).
pancreas (1 paper, 2017). "Exocrine pancreas degeneration has also been described in several mouse models with ciliary defects including Ift88 and Pkd1." (PMID 28410364, 2017).
IFT88 also shares sentences with these, for which no sentence is quoted: bacterial infection (2 papers); cleft palate (2); peripheral neuropathy (2); atherosclerosis (1); cardiomyopathy (1); chondrosarcoma (1); cleft lip (1); deafness (1); endometrial cancer (1); genetic disease (1); holoprosencephaly (1); Hypertension (1); Immunodeficiency (1); intracranial hemorrhage (1); lipomatosis (1); lung adenocarcinoma (1); neuropathy (1); prostate carcinoma (1); pulmonary hypertension (1); rheumatoid arthritis (1); schwannoma (1); Usher syndrome (1); uterine corpus endometrial carcinoma (1).